COL15A1 (collagen type XV alpha 1 chain)
Diseases named in the same sentence as COL15A1 in open-access papers (continued):
Sharing a sentence is not in itself a finding about the gene and the disease.
osteoporosis (1 paper, 2025). A condition of reduced bone mass, with decreased cortical thickness and a decrease in the number and size of the trabeculae of cancellous bone (but normal chemical composition), resulting in increased fracture incidence. "Another study found that COL15A1 is a candidate gene for further studies to evaluate the genetic susceptibility to osteoporosis." (PMID 40176796, 2025).
prostate adenocarcinoma (1 paper, 2024). "However, the variation in COL15A1 expression between cancers and normal tissues was not statistically significant in some malignancies, such as prostate adenocarcinoma (PRAD) and rectum adenocarcinoma (READ)." (PMID 39088036, 2024).
sarcopenia (1 paper, 2024). Progressive decline in muscle mass due to aging which results in decreased functional capacity of muscles. "The COL15A1 gene has been identified as one of the genes with shared genetic co‐localization evidence in relation to sarcopenia, and the increased COL15A1 is a risk factor for sarcopenia." (PMID 38644354, 2024). "Upon evaluating the clinical development potential of these drug target genes, we found zinc supplementation and collagenase clostridium histolyticum might be potential therapeutics for sarcopenia by activating HP and inhibiting COL15A1, respectively." (PMID 38644354, 2024). "Drug repurposing analysis supported zinc supplementation and collagenase clostridium histolyticum might be potential therapeutics for sarcopenia by activating HP and inhibiting COL15A1, respectively." (PMID 38644354, 2024). "These two drugs might be potential therapeutics for sarcopenia by activating HP and inhibiting COL15A1, respectively." (PMID 38644354, 2024). "Theoretically, inhibiting the COL15A1 is a potential therapeutics for sarcopenia." (PMID 38644354, 2024). "Based on these integrated datasets, our study provides potential evidence for the genetic colocalization of six drug target genes (HP, HLA‐DRA, MAP 3K3, MFGE8, COL15A1, and AURKA) with sarcopenia." (PMID 38644354, 2024). "The results revealed that six potential druggable genes (HP, HLA‐DRA, MAP 3K3, MFGE8, COL15A1, and AURKA) passed the colocalization analysis and were present in more than one QTL datasets or sarcopenia‐related traits." (PMID 38644354, 2024). "Our research indicated MAP 3K3, MFGE8, COL15A1, HP, and HLA‐DRA may serve as promising targets for sarcopenia, while the effectiveness of zinc supplementation and collagenase clostridium histolyticum for sarcopenia requires further validation." (PMID 38644354, 2024).
Skeletal myopathy (1 paper, 2019). "Mice deficient of COL15A1 expression show exercise-induced skeletal myopathy and cardiovascular defects." (PMID 31783652, 2019).
testicular seminoma (1 paper, 2025). A malignant germ cell tumor arising from the testis. "Emerging research evidence indicates that elevated expression levels of COL15A1 significantly inhibit the migratory capacity and metastatic potential of testicular seminoma cells." (PMID 40176796, 2025).
thoracic aortic aneurysm (1 paper, 2025). An aneurysm formed in the wall of the proximal portion of the descending aorta proceeding from the arch of the aorta. "Moreover, COL15A1 variants associate with disease severity in families with syndromic thoracic aortic aneurysms, suggesting a genetic modifier role." (PMID 39932797, 2025).
ventricular dilatation (1 paper, 2026). "In addition, the echocardiographic data indicate that, 1 week after AMI, ventricular dilatation was accelerated and stronger in the Col15a1−/− mice than in the WT ones." (PMID 40832756, 2026).
tumor (21 papers, 2009 to 2026). "This isn't to say that other types of gene alterations can’t cause COL15A1 to cause poor tumor prognosis." (PMID 39088036, 2024). "Meanwhile, gene co-expression assessments were utilized to look into the association between the expression of COL15A1 and immune-related genes in 33 different tumor types." (PMID 39088036, 2024). "Kaplan–Meier survival analysis showed that higher expression levels of Col15a1 gene transcripts in low grade tumours associate with better relapse free survival, while in high grade tumours they associate with poor survival." (PMID 34576139, 2021). "We present here data on the impact of the BM-zone associated ColXV on carcinogenesis using our Col15a1 knockout mice subjected to both autochthonous and transplantable tumour models." (PMID 34576139, 2021). "Our findings revealed that COL15A1 expression was substantially linked with CAFs, implying that COL15A1 may influence tumor growth in the TME through modulating immunological, stromal, and CAF cells." (PMID 39088036, 2024). "We couldn't find any beneficial information in the prior literature because there had been few investigations on the association between COL15A1 and tumor immune cells." (PMID 39088036, 2024). "Among the eight chemotherapeutics, except Hydrastinine (Cor = 0.433, p < 0.001) and Bisacodyl (Cor = 0.281, p = 0.030), the sensitivity of most drugs to tumor cells is significantly negatively correlated with COL15A1 expression levels." (PMID 39088036, 2024). "IHC staining of normal stomach, kidney, liver, and pancreatic tissues revealed modest COL15A1 staining, whereas tumor tissues revealed significant staining." (PMID 39088036, 2024). "As a result, we evaluate the differences in COL15A1 expression levels in diverse malignancies and their link with tumor prognosis using several databases such as TCGA, cBioPortal, Human Protein Atlas (HPA), and Genotype Tissue-Expression (GTEx)." (PMID 39088036, 2024). "The greatest significant variations in COL15A1 expression between normal and tumor tissues were found in the KIRC and THYM groups." (PMID 39088036, 2024). "All of these findings imply that there is a statistically significant relationship between COL15A1 expression levels and tumor stage, as well as patient age, in specific types of tumors." (PMID 39088036, 2024). "The researchers used gene set enrichment analysis (GESA) to scrutinize the biological importance of COL15A1 expression in various tumor tissues and to explain how the gene in question influenced the incidence of malignancies via functions or pathways." (PMID 39088036, 2024). "Normal cervix and ovary tissues, on the other hand, showed significant COL15A1 staining, whereas tumor tissues showed only moderate staining." (PMID 39088036, 2024). "Re-expression of COL15A1 in the HeLa cell line hindered tumor formation in a xenograft model, and the ability of COL15A1 to stabilize the extracellular matrix also prevented distal tumor metastasis." (PMID 35493106, 2022). "To investigate the in vivo roles of ColXV in mammary tumourigenesis, we crossed Col15a1−/− mice with the MMTV-PyMT model and compared tumour development in the PyMT;Col15a1−/− crosses with the wild-type MMTV-PyMT (PyMT) mice from 4 weeks up to 14 weeks of age." (PMID 34576139, 2021). "In the PyMT;Col15a1−/− tumours, the stromal ECM was more often loosely packed than in the controls, and contained non-fibrillar protein deposits which also accumulated on collagen fibrils." (PMID 34576139, 2021).
tumor (continued). "Ultrastructural analysis revealed locally thicker BMs and protein aggregates around capillaries in the PyMT;Col15a1−/− tumours, similar to what has been observed in heart capillaries." (PMID 34576139, 2021). "PyMT;Col15a1−/− tumour capillaries were typically covered with regions of both protein aggregates and normal looking BM." (PMID 34576139, 2021). "Our key findings in the PyMT model are that ColXV can suppress primary tumour growth in wild-type PyMT mice and that the deletion of Col15a1 leads to the aberrant organisation of the interstitial tumour matrix." (PMID 34576139, 2021). "Compared with intact healthy vessels, we found morphological abnormalities in the capillaries of both control PyMT and PyMT;Col15a1−/− tumour samples." (PMID 34576139, 2021). "We performed differential analysis and correlation analysis of these four genes (COL3A1, COL4A1, COL5A1, and COL15A1) and tumor immune subtypes with tumor microenvironment scores." (PMID 34691289, 2021). "Although common tumor EC genes such as Nid2 and Col15a1, were detected in s.c. and liver tumor-derived ECs, two distinct clusters formed based on the site of tumor growth (i.e., s.c. and liver)." (PMID 32440964, 2020). "This difference was also validated by the expression levels of COL15A1 in distinct tumor tissues." (PMID 39088036, 2024). "Recently, mounting evidence has shown that COL15A1 also had an impact on tumor growth and invasion." (PMID 39088036, 2024). "Furthermore, we analyzed the potential relation between COL15A1 expression levels and tumor prognosis in 33 types of tumors from MSI, TMB, immune infiltration levels, and GSEA enrichment assessment." (PMID 39088036, 2024). "Moreover, we discovered a considerable correlation between COL15A1 expression and tumor stage in certain cancer types, including HNSC, KIRC, TGCT, and KIRP." (PMID 39088036, 2024). "Our study suggests that COL15A1 may serve as a prognostic marker for malignancy because of its differential expression in tissues and their function in tumor immunity." (PMID 39088036, 2024). "Interestingly, while three key genes were significantly upregulated in tumor samples, COL15A1 played a role as a favorable factor, while the other two served as risk factors." (PMID 35493106, 2022). "Moreover, picrosirius red staining revealed a slight but not significant increase in the relative ratio of thin to thick collagen fibres in PyMT;Col15a1−/− tumours, indicating more immature collagen fibres in these than in the wild-type tumours." (PMID 34576139, 2021). "Moreover, we assessed the influence of Col15a1 deletion in tumour growth using common syngeneic mouse models for the C57BL6 background." (PMID 34576139, 2021). "Tumour cell proliferation analyses with two different antibodies showed a trend towards higher proliferation in early-stage PyMT;Col15a1−/− tumours collected from mice at the ages of 6–9 weeks than in controls of the same stage, but lower proliferation in late-stage tumours at weeks 10–14." (PMID 34576139, 2021). "Therefore, the data from cellminer was used to explore the relationship between COL15A1 expression levels and drug sensitivity, and the eight most sensitive drugs, which may be beneficial to the tumor patient's prognosis, were selected to present the analysis results." (PMID 39088036, 2024). "However, quantification of the CD-31 signals in the same microscopic fields by automatic image analysis showed equally large CD-31-positive areas in the samples, suggesting that PyMT;Col15a1−/− tumours may contain fewer but larger blood vessels than control tumours." (PMID 34576139, 2021). "COL3A1, COL1A2, COL15A1, ASPN, and MXRA5 were higher expressed in tumor samples, while OGN was lower expressed." (PMID 32300359, 2020). "Our findings suggest that COL15A1 may be a predictive factor for cancer and that tumor-infiltrating immune cells, TMB, and MSI may influence COL15A1’s role in tumor immunity." (PMID 39088036, 2024).
tumor (continued). "This could mean that COL15A1 expression levels can alter the TMB and MSI of the tumor, thereby impairing patient response to immune checkpoint inhibitor therapy and resulting in poor tumor prognosis." (PMID 39088036, 2024). "We found less and loosely organised fibrillar collagen matrix in the PyMT;Col15a1−/− tumours in comparison with PyMT control tumours and the presence of non-fibrillar protein aggregates in the tumour stroma." (PMID 34576139, 2021). "Aggregates were not evenly distributed over the entire length of the PyMT;Col15a1−/− tumour vessels, and their thickness varied from 100 nm to even 1500 nm (mean thickness 297 ± 220nm)." (PMID 34576139, 2021). "However, prior research on the involvement of COL15A1 in cancers has been focused on individual tumor types rather than a pan-cancer examination of the relationship between COL15A1 and diverse tumors." (PMID 39088036, 2024). "In the tumour stroma, however, the integrity of endothelial cells was compromised in both genotypes, and reliable assessment of recurrent changes, such as those in endothelial cell–cell junctions, was not possible in the PyMT;Col15a1−/− tumours in relation to the PyMT control tumours." (PMID 34576139, 2021). "The most consistent, exclusive and highly prevalent finding in the PyMT;Col15a1−/− tumours was accumulation of non-fibrillar protein aggregates on the capillary BM, making it locally excessively thick, similar to those observed in the heart tissue capillaries of the Col15a1−/− mice." (PMID 34576139, 2021). "On the other hand, Col4a1, Col4a3, Col4a5, Col5a3, Col11a2, Col14a1, Col15a1, Col16a1, and Col22a1 were found in normal ECM but not in tumor ECM; Col25a1 was found only in tumor ECM but not in normal ECM." (PMID 36547361, 2022).
cancer (16 papers, 2018 to 2025). A tumor composed of atypical neoplastic, often pleomorphic cells that invade other tissues. "Almost all immune-related genes were positively linked with COL15A1 in most cancers, according to the findings, which were shown as heatmaps." (PMID 39088036, 2024). "UCEC (p = 2.1e−0.7), BRCA (p = 0.00014), SARC (p = 0.0061), BLCA (p = 0.019), LIHC (p = 0.02), and THYM (p = 0.02) were the six cancers studied that were most linked with COL15A1 expression levels to present the findings." (PMID 39088036, 2024). "Furthermore, in diverse cancer types, COL15A1 expression levels were substantially linked with TMB, MSI, and immune cell infiltration." (PMID 39088036, 2024). "Furthermore, we discovered that COL15A1 expression levels were substantially linked with MMR in the majority of cancers, including DLBC and PAAD." (PMID 39088036, 2024). "In KIRP and MESO, however, increased COL15A1 expression is linked to a poor prognosis, suggesting that COL15A1 could be a risk factor for individuals with these cancers." (PMID 39088036, 2024). "Based on data from the UCSC, we evaluated the expression levels of COL15A1 in 33 cancers and normal tissues." (PMID 39088036, 2024). "COL15A1 expression was favorably linked with stromal cells and immune cells in TME of different cancers, according to a research of ESTIMATE scores." (PMID 39088036, 2024). "We discovered many genes (SLIT3 and HSPG2) which were co-expressed with COL15A1 across various cancers and tissues using STRING and GEPIA2." (PMID 39088036, 2024). "To conclude, our pan-cancer analysis divulged substantial discrepancies in COL15A1 expression across normal and malignant tissues, and also a link between COL15A1 expression and clinical prognosis." (PMID 39088036, 2024). "Through the literature search, we were unable to retrieve any articles on pan-cancer analysis of COL15A1 from the perspective of overall tumors." (PMID 39088036, 2024). "To examine the biological roles of COL15A1 in tumors, we looked at the relationship between COL15A1 and cancer fibroblasts, and drug sensitivity." (PMID 39088036, 2024). "In the diverse sorts of cancers, detection of the closeness between COL15A1 expression and DFI was carried out, including ACC (p = 0.035), CESC (p = 0.003), KIRP (p = 0.006), PAAD (p = 0.004)." (PMID 39088036, 2024). "Some ECM structural proteins, including Col5A1 and Col15A1, were downregulated in the cancer-conditioned fibroblasts in our cell culture experiments." (PMID 37903851, 2023). "The highest expression of genes encoding Col1a1-2, Col3a1, Col4a1, Col4a2, Col5a1, Col5a2, Col6a1, Col8a1, Col9a3, Col10a1, Col12a1, Col14a1, Col15a1, Col16a1, Col18a1, and Col28a1 were detected in untreated tumors, whose landscapes were dominated by Krt8+ cancer cells." (PMID 39372930, 2024). "However, because we conducted a comprehensive pan-cancer analysis, more investigation is essential to understand the precise molecular performance of COL15A1 in carcinogenesis." (PMID 39088036, 2024). "In addition, the expression levels of COL15A1 was assessed in several carcinomas and were classified from high to low in terms of their significance." (PMID 39088036, 2024). "Several of the top SNPs are in genes associated with PCa or PCa processes, including MKI67 (rs8473), PCSK6 (rs80278342), ABCB6 (rs60322991), and TCHP (rs11068997); or other cancer-associated processes, including GGA2 (rs1135045), H1-5 (rs11970638), and COL15A1 (rs2075662)." (PMID 38052806, 2023). "Consequently, we explored the link between TME and COL15A1 expression levels across cancer types." (PMID 39088036, 2024). "Furthermore, the role of COL15A1 is different in various cancers due to the biodiversity." (PMID 39088036, 2024). "Except for the cancers for which no normal tissue data is available, COL15A1 expression in tumors and normal tissues differs considerably in all but one of the 19 tumors studied." (PMID 39088036, 2024).
cancer (continued). "Although the growing number of investigations demonstrating the indispensable role of COL15A1 in the progression of certain tumors, no pan-cancer assessment of COL15A1 is accessible to date." (PMID 39088036, 2024). "The extended analysis of top seven collagen genes among 11 cancer types shows a consistent positive correlation between the fractions of endothelial cells and expression of basement membrane (COL4A1 and COL4A2) and multiplexin (COL15A1) collagen subfamily." (PMID 36321857, 2022). "Therefore, our database-based pan-cancer analysis suggests that these four collagen family genes (COL5A1, COL3A1, COL4A1, and COL15A1) have commonality with the progression of various tumors." (PMID 34691289, 2021). "Some genes (e.g. SPINK1 in MAY and ANO4, KCTD8, COL15A1, and KCNH1 in ZMA) are related to cancer and skin properties and may have played a role in adaptation to Mayotte and Madagascar climates by increasing tolerance to thermal stress, humidity, and UV exposition." (PMID 35137043, 2022). "In addition, the strict scale in the present study to only analyze the proteins detected in all examined samples ruled out some important DEPs such as cancer-related proteins, which changed dramatically during carcinogenesis, such as Cacna1b, Col15a1, Hmgcr, Zfp82, and Znrd1-as." (PMID 32792008, 2020).
myopathy (3 papers, 2011 to 2023). A disease of the muscle in which the muscle fibers do not function properly. "For example, Col6a1–deficient and Col15a1-deficient mice have a muscle phenotype that strongly resembles human myopathies." (PMID 21909251, 2011). "Drosophila Mp mutants, like the Col15a1−/− mice, showed progressive deterioration of muscular function and myopathy." (PMID 33543021, 2020). "Therefore, one may hypothesize that the mild myopathy observed in the Col15a1−/− mice could be partly related to the perfusion defect in the striated skeletal muscles." (PMID 33543021, 2020). "Interestingly, Col15a1 knockout mice lacking collagen type XV demonstrate a myopathy vulnerable to exercise-induced muscle injury, suggesting that this collagen type is required for muscle homeostasis." (PMID 37773216, 2023).
heart disease (2 papers, 2021 to 2025). "Due to the expression of COL15A1 in the heart and blood vessels, its mutation may be associated with heart disease, especially with abnormal myocardial morphology and physiology." (PMID 40176796, 2025).